PECAM1 (platelet and endothelial cell adhesion molecule 1)
Diseases named in the same sentence as PECAM1 in open-access papers (continued):
Sharing a sentence is not in itself a finding about the gene and the disease.
tumor (3,774 papers, 1997 to 2026). "Previous studies have implicated PECAM1 in tumor cell migration, proliferation, and anchorage-independent growth—hallmarks of metastatic potential." (PMID 40361912, 2025). "PECAM1 downregulation has been shown to mediate the secretion of metallopeptidase inhibitor 1, a protein linked to tumor cell proliferation." (PMID 40563443, 2025). "CD31 (PECAM1), an endothelial marker essential for angiogenesis, facilitates neovascularization and has been implicated in tumor progression across multiple cancers." (PMID 41372989, 2025). "This reduction in VEGFA expression was associated with a substantial inhibition of tumor angiogenesis, as indicated by the diminished PECAM1/CD31 staining." (PMID 39477683, 2025). "Tumor vessel endothelial abnormalities in thrombocytopenic mice bearing AT-3 were associated with an increase in plasma PECAM-1 as compared to AT-3-bearing control mice." (PMID 38493157, 2024). "The number of tumor-associated vessels and Pecam1 mRNA in microdissected LLC tumors were increased in endFoxf1+/− lungs compared to controls." (PMID 38589650, 2024). "The protein encoded by the PECAM1 gene is an endothelial cell marker used to evaluate tumor microvessels and vascular density." (PMID 35454802, 2022). "As for tumor associated endothelial cells, that highly expressed marker gene PECAM1, we obtained in six clusters after machine learning." (PMID 35733218, 2022). "PECAM1 encodes a protein associated with angiogenesis and extracellular circulation that is involved in tumour growth and spread." (PMID 34358255, 2021). "In order to examine the possibility that End‐MyoT TECs stimulated tumor angiogenesis, we studied the formation of tumor‐associated vasculature by staining the sections from xenograft tumors using anti‐PECAM‐1 antibody." (PMID 31094056, 2019). "More research needs to be conducted to test anti-PECAM-1 IONPs in a brain metastasis model and investigate how they associate with the blood tumor barrier and tumor cells." (PMID 24278373, 2013). "PECAM-1 staining showed an increase in the number of tumor associated vessels in the WT as compared to KO animals." (PMID 17650334, 2007). "Additionally, PECAM1 expression was inversely correlated with tumor purity and positively associated with the infiltration of multiple immune cell subsets, including T cells, B cells, and macrophages." (PMID 40361912, 2025). "Interestingly enough, SPP1 expression was inversely correlated to PECAM1 (encoding for the endothelial marker CD31) in tumor and healthy LUAD TCGA samples." (PMID 40028673, 2025). "Moreover, PECAM1 is closely associated with angiogenesis, which is another essential process for tumor growth and metastasis." (PMID 40361912, 2025). "PECAM-1 is expressed in some tumor cells and has been linked to tumor invasion." (PMID 36816016, 2023). "Eighteen genes that potentially play pivotal roles in the pathogenesis of LC and may be closely associated with tumor progression, especially PECAM-1, were identified in the present study." (PMID 33828969, 2021). "CD68 was used as a marker of TAM infiltration, reflecting changes in immune cell presence within the tumor while PECAM-1 staining was used to assess vessel density and normalization in response to therapy." (PMID 40802092, 2026). "We further identified that MES‐like cells sheltered in the vicinity of PECAM1+ tumor vascular niches correlated with local HBEGF upregulation." (PMID 41181988, 2026). "By correlation analysis, a tendency (r = 0.52; p = 0,08) for a positive relationship between FAP expression and PECAM1/CD31-positive vascular tumor areas was identified." (PMID 40694103, 2026). "In all tumors, a heterogeneous expression of PECAM1/CD31 as a marker for vascular components and Vimentin, reflecting the mesenchymal and stromal characteristics of the tumor, was observed." (PMID 40694103, 2026). "CD31 (PECAM-1) is a well-established endothelial cell marker used to assess microvessel density and tumor angiogenesis." (PMID 40943297, 2025).
tumor (continued). "Compared with the peritumor area, CCL21, CCL19 and Pecam1 were more highly expressed in the tumor area, whereas Lyve1 had lower expression." (PMID 40685403, 2025). "The genes that most characterize EndMT in different tumor types are PECAM1, VWF, CD34, CDH5, MCAM, and CLDN5/11." (PMID 40650130, 2025). "It has known roles in the immune response to tumors; the expression of PECAM1 can impact the infiltration of immune cells into the tumor microenvironment, which is a crucial factor in the immune surveillance of cancer." (PMID 40361912, 2025). "Several hub genes, such as CDH5, CLDN5, VWF, and PECAM1, were significantly upregulated, reflecting their established involvement in vascular development and tumor progression." (PMID 41008787, 2025). "In the tumor progression from non-invasive to invasive cancer, infiltration of endothelial cells (PECAM1) and macrophages (CD68) was noted in the tumor interior, in addition to increased chemokine signaling (CXCR4)." (PMID 39965034, 2025). "Four primary cell populations were first identified using canonical cell markers: WT tumor cells (WT1, NCAM1, SIX1, SIX2, PAX2), cancer-associated fibroblasts (CAFs) (ACTA2, TAGLN, COL1A1, PDGFRB), endothelial cells (PECAM1, CLDN5, ENG, VWF) and immune cells." (PMID 40098972, 2025). "IHC of postoperative pathological sections confirmed high expression of ERG, FLI1, CD34 and PECAM1 in tumor cells." (PMID 41445863, 2025). "Kaplan-Meier analysis revealed that patients with high PECAM1 expression had significantly worse prognosis than those with low expression (p = 0.003; HR = 5.05, 95% CI: 1.71–14.9), supporting the link between CD31 and aggressive tumor behavior." (PMID 41372989, 2025). "Immunostainings for PECAM-1, VE-cadherin, and ZO-1, all gave concordant results, revealing major alterations of the tumor vessel endothelium, specifically in AT-3 tumors from thrombocytopenic mice." (PMID 38493157, 2024). "Endothelial cells were unequivocally identified by PECAM1 expression (immunohistochemically) in the same sections stained with hematoxylin/eosin to show xenograft tumor histology." (PMID 39458030, 2024). "Immunohistochemical staining (IHC) of omental tumor sections from untreated MOVCAR 5009-bearing mice with anti-PECAM-1/CD31 mAb revealed a chaotic blood vessel network with high MVD and small luminal diameters compared to the OV-treatment groups." (PMID 39372930, 2024). "PECAM1, upon phosphorylation during cellular aggregation, promotes proliferation by inducing anoikis resistance in tumor cells." (PMID 38802480, 2024). "PECAM1 expression was also closely associated with ETS1/PLAT and CD274 (PDL1)/IFNGR1, indicating close involvement of tumor angiogenesis with unique proteolysis and tumor immunity." (PMID 38557819, 2024). "Several cell adhesion receptors, such as CD44 and PECAM1 (Platelet Endothelial Cell Adhesion Molecule 1), were highly expressed in tumor samples." (PMID 38979413, 2024). "PECAM-1 staining of tumor sections revealed that the quantity of tumor vessels per unit area remained consistent in the TβRIIiΔEC mice when compared with that in the control mice." (PMID 39758992, 2024). "After embedding xenograft tumor tissues in paraffin and preparing tissue sections, hematoxylin–eosin (HE), Ki-67, and CD31 (platelet and endothelial cell adhesion molecule 1) staining were performed for IHC." (PMID 38012281, 2023). "CD31, also known as platelet endothelial adhesion molecule 1 (PECAM1), is commonly as a marker of endothelial cells to demonstrate the presence of endothelial tissue and evaluate tumor angiogenesis." (PMID 37626402, 2023). "Studies of the molecular mechanism of PECAM-1 have shown that PECAM-1 mediates the release of soluble mediators that stimulate in vitro tumor cell proliferation." (PMID 36688087, 2023). "This prostaglandin stimulates the pro‐angiogenic factors such as VEGF, FGF and so forth, and certain adhesion molecules like PECAM‐1 in tumour ECs." (PMID 37156724, 2023).
tumor (continued). "We performed CD31 (PECAM1) immunostaining for histological analysis of blood vessels formed within the tumor." (PMID 38102691, 2023). "We proved that Cy5/Epacasome-2 (red signal) migrated farther away from the blood vessels (platelet endothelial cell adhesion molecule 1 (PECAM1), green signal) and distributed throughout the tumour sections better than EPA/Lipo-SM/Chol." (PMID 37945606, 2023). "We observed a decrease in mRNA expression of vascular and angiogenic molecules such as mouse Pecam1, Mcam, Pdgf-β receptor, Vegf-a, and the lymphangiogenic growth factors Vegf-c in tumor-bearing mice treated with anti-sMCAM antibody relative to IgG." (PMID 38137406, 2023). "PECAM-1 is also involved in the process of tumor metastasis and can be used as a prognostic marker for secondary tumor lesions." (PMID 35366289, 2022). "PECAM-1 expression in endothelial cells promotes tumor cell proliferation in transwell co-cultures and in vivo." (PMID 35884405, 2022). "PECAM1, platelet endothelial cell adhesion molecule 1 (CD31), is involved in tumor angiogenesis and endothelial cell migration." (PMID 35454802, 2022). "To further validate the connection between Nanog expression and dormancy in vivo, we evaluated the CD31 (also called PECAM1), an endothelial marker of blood vessel, and Nanog expression in tumor-bearing mouse and human CRC tissues by IF." (PMID 35177584, 2022). "Clustered stromal cells corresponded to endothelial cells (positive for PECAM1/CD31, VWF), normal fibroblasts (FN1, EGFL6), tumor-associated fibroblasts (TAFs; PDGFRA, ADH1B), and thymic epithelial cells (TECs; KRT19, S100A14)." (PMID 35869073, 2022). "The R2cKO mice showed poor angiogenesis in tumors formed by transplantation with sarcoma or melanoma cells, as suggested by decreased tumor weight and decreased expression of endothelial markers, such as PECAM1, VEGFR2/KDR, and VEGF." (PMID 35130955, 2022). "PECAM-1 was also identified in NGS as being downregulated in breast TECs vs. breast NECs, which underlines the fact that the tumor microenvironment alters the EC phenotype." (PMID 34445568, 2021). "The mRNA transcription and the protein expression levels, we found that PECAM1 expression was significant down-regulated in LUAD tumor tissues." (PMID 33461176, 2021). "We further analyzed the relationship between PECAM1 expression and molecular markers of tumor-infiltrating immune cells." (PMID 33461176, 2021). "Endothelial cells in tumor vasculature are known as tumor ECs (TECs), showing cytogenetic abnormalities of chromosomal aneuploidy and abundant expression of CD31 (platelet endothelial cell adhesion molecule‐1, PECAM‐1)." (PMID 34455700, 2021). "Through using qRT-PCR, it demonstrated that the expression of PECAM1 were down-regulated in tumor tissues." (PMID 33461176, 2021). "In four analyses, the mRNA levels of PECAM1 in tumor samples were lower than those in normal samples (P < 0.05)." (PMID 33461176, 2021). "The IHC staining of PECAM1 demonstrated that the blood vessel density in H. pylori (+) tumor tissues was significantly higher than that in H. pylori (+) nontumor tissues." (PMID 34390328, 2021). "We found that high CLEC14A/PECAM1 and CLEC14A/TIE1 ratios (ratio above 95% of controls) were significantly associated with tumour pathology (odds ratio = 2.5113, 95% CI: 1.7467–3.6104 and odds ratio = 8.9821; 95% CI: 6.7440–11.9630 respectively)." (PMID 32696621, 2020). "CLEC14A expression in tumour tissues (normalised to PECAM1 or TIE1 expression) is also significantly above most, but not all, non‐tumour pathologies." (PMID 32696621, 2020). "The data indicate that even within the same tumour, tissue vascularity (as defined by PECAM1 expression) is highly variable as is CLEC14A expression." (PMID 32696621, 2020).
tumor (continued). "The expression of PECAM-1 in tissues can be applied to assess the extentof tumor angiogenesis.VEGF, originally known as vascular permeability factor, is a signaling proteinproduced by cells that stimulates the formation of blood vessels." (PMID 33152052, 2020). "Increased HB-EGF secretion in HLMFs, which upregulate α-SMA, markedly increases tumor formation of CC cells and tumor invasion in vivo by EGFR activation-mediated upregulation of PECAM-1 and activation of STAT3/ERK." (PMID 32708604, 2020). "Subsequently, we measure CCND1 and PECAM1/CD31 expression level in three pairs of ccRCC tumor and normal samples." (PMID 31850854, 2019). "Platelet and endothelial cell adhesion molecule 1, (PECAM1, also named CD31), encodes a protein involved in several processes of primary tumor growth and proliferation, including angiogenesis, vascular permeability, and extracellular circulation." (PMID 31850854, 2019). "Nevertheless, studies have shown that the expression of some adhesion molecules on these vessels, such as PECAM-1, possibly allowing circulating cells to interact with these tumour vessels." (PMID 31212986, 2019). "We conducted fluorescent immunohistochemical analysis of the xenografted tumor tissues to determine the expression levels of platelet and endothelial cell adhesion molecule 1 (PECAM1), an indicator of vascular proliferation." (PMID 31354472, 2019). "Analysis of tumor vascularization on day 11 revealed a slight decrease of PECAM-1-positive cells in tumors of EMB animals compared to Sham controls." (PMID 31601175, 2019). "The tumours were then excised and the underlying membrane was probed using an FITC-conjugated rabbit polyclonal anti-PECAM-1 antibody." (PMID 31000751, 2019). "To confirm CTNNA2 mediated angiogenesis inhibition in vivo, we performed CD31/PECAM-1 (Platelet Endothelial Cell Adhesion Molecule-1) immunohistochemical staining on tumor sections from mice and counted the blood vessels." (PMID 31489113, 2019). "Tumour cells arrested preferentially in vascular branching points and left the junctions intact in the first 4 days, as assessed by PECAM-1 (platelet and endothelial cell adhesion molecule) and claudin-5 immunostainig and TEM." (PMID 31426859, 2019). "Anti-PECAM-1 therapy was shown to inhibit the progression of already developed tumor metastases by reducing proliferation." (PMID 31344919, 2019). "To summarize, we, for the first time, confirmed that CD300A promoted tumor progression by increase PECAM1 and ADCY7 expression, and activating the AKT/mTOR signaling pathway in AML." (PMID 29938007, 2018). "We assessed the platelet and endothelial cell adhesion molecule (PECAM)-1-positive vascular surface area in each tumor using an image analyzer." (PMID 29707135, 2018). "Staining of tumor xenografts with anti-CD31/PECAM1 revealed that fibroblasts markedly enhanced the vessel size at the tumor periphery and in the tumor core." (PMID 28423685, 2017). "PECAM1 inhibition has been suggested as a therapeutic approach that targets the tumor microenvironment to suppress the end stages of metastatic progression, which has until now been a refractory clinical entity." (PMID 28915696, 2017). "Tumour vascularity was assessed using CD31 (PECAM-1) immunohistochemistry, identifying the number of vascular structures per HPF." (PMID 29156557, 2017). "It is also expressed in certain tumours, which can imply a rapidly growing tumour because of its involvement in angiogenesis, for this reason PECAM-1 has been used as an angiogenic target in cancer therapies." (PMID 28522939, 2017). "Immunohistochemistry of tumor tissues showed that RLYE treatment resulted in dose-dependent decrease in staining with FITC-isolectin B4 and an anti-CD31 (PECAM-1) antibody, indicating that the peptide inhibits tumor angiogenesis." (PMID 28052029, 2017).
tumor (continued). "Re-introduction of AP-2α (a transcriptional repressor of PECAM1) in PECAM1+ cancer cells abolishes tube-forming ability, whereas AP-2α knockdown in PECAM1− tumor cells upregulates PECAM1 expression and promotes tube formation." (PMID 27608016, 2016). "Curcumin-induced inhibition of tumor growth and angiogenesis in mouse model was related to down-regulating the expression of cyclin D1, platelet endothelial cell adhesion molecule-1 (PECAM-1), and p65." (PMID 27529277, 2016). "Next, we assessed primary tumor vascularity via immunohistochemistry staining of CD31 (PECAM-1), a commonly used marker of endothelial cells." (PMID 27841282, 2016). "Tumor hypoxia (i.e., pimonidazole uptake) showed an inverse correlation with blood vessel density, as determined by CD31/PECAM-1 co-staining." (PMID 27800026, 2016). "Another study demonstrated that PEITC suppressed androgen-responsive tumor growth in vivo, possibly by downregulation of integrin family proteins (β1, α2, and α6) and tumor platelet/endothelial cell adhesion molecule (PECAM-1/CD31)." (PMID 27651838, 2016). "To confirm the anti-angiogenic effects of sMEK1 on tumor angiogenesis in vivo, we next counted the number of blood vessels in the vasculature using CD31 (PECAM-1) immunostaining of endothelial cells." (PMID 26378810, 2015). "Tumor-associated angiogenesis, another critical hallmark of GBM, as assessed by PECAM1 protein staining, was significantly increased in HOXA9-positive tumors." (PMID 25762636, 2015). "Our results showed that in tumours of curcumin-treated group, there were significant reductions in the expression of PECAM-1, cyclin D1, and p65 compared to the control group." (PMID 25879038, 2015). "The achievement of specific targeted silencing of the PECAM-1 gene in tumor xenografts is possibly due to the strong bioavailability of the siRNACD31-lipoplexes of the neovascular cells in the TME." (PMID 24959215, 2014). "Further investigations have to clarify the therapeutic role of PECAM-1 in the treatment of fibrosis and correlating tumour growth." (PMID 24734240, 2014). "We further investigated the effect of XAF1 tumor angiogenesis in vivo, and determined the expression of PECAM-1/CD31, a well-established endothelial cell marker in tumor tissues treated with Ad5/F35-XAF1 and Ad5/F35-Ctrl." (PMID 24980821, 2014). "Immunofluorescence staining of tumour sections for the endothelial cell marker CD31 (also known as PECAM1) revealed that tumours derived from empty vector control cells contained CD31-positive structures consistent with blood vessels." (PMID 25179601, 2014). "The use of vasculature-targeting antibodies, especially against PECAM-1, has been utilized before for lung targeting, injury treatment, and as tumor contrast agents." (PMID 24278373, 2013). "Although the possibility that PECAM-1 bound heparan sulfate was controversial for many years, it is now clear that the hypoxic conditions found in tumours would favour this interaction." (PMID 22272201, 2012). "PECAM-1 staining of tumor tissue sections to study tumor vasculature revealed that gemcitabine, bevacizumab, sunitinib and EMAP all caused a significant reduction in microvessel density compared with control." (PMID 22723862, 2012). "We found that dietary treatment with PEITC significantly inhibited tumor platelet/endothelial cell adhesion molecule (PECAM-1/CD31) expression, a marker of angiogenesis." (PMID 22266918, 2012). "In analyzing tumor vascularization by immunofluorescence staining for endothelial cell marker PECAM-1, the microvessels of HSA/TIMP-2-treated tumor tissue demonstrated a significant 39.2% decrease in PECAM-1 level compared with the control group (P<0.01)." (PMID 22545131, 2012). "Treatment with PEITC resulted in significantly lower microvessel density, as indicated by PECAM-1/CD31 staining intensity in the tumor." (PMID 22266918, 2012).